CRP (C-reactive protein)
Diseases named in the same sentence as CRP in open-access papers (continued):
Sharing a sentence is not in itself a finding about the gene and the disease.
periodontitis (continued). "Although evidence directly tying periodontitis to systemic disease via increased circulating cytokines is lacking, some studies, both clinical and pre-clinical, have reported that periodontitis-induced increases in serum IL-6 and CRP levels can lead to endothelial dysfunction." (PMID 31293577, 2019). "Periodontitis, one of the major types of infection-driven inflammation, often co-occurs in the in the hemodialysis population and correlates with markers of malnutrition and inflammation, such as albumin, creatinine, and C-reactive protein." (PMID 31683838, 2019). "The study demonstrated that severe chronic periodontitis was associated with increased serum hs-CRP, but not with any significant elevation of TNF- α or CRP." (PMID 31336777, 2019). "Periodontitis, one of the major types of infection-driven inflammation, often co-occurs in the hemodialysis population and correlates with markers of malnutrition and inflammation, such as albumin, as well as creatinine and C-reactive protein." (PMID 31683838, 2019). "In addition, patients in the periodontitis group showed higher median CRP levels (0.41 (0.35; 0.49)) compared to healthy controls (0.33; (0.27; 0.35), p < 0.001)." (PMID 31817862, 2019). "It has previously been hypothesized that several inflammatory mediators are systemically released during periodontitis, including CRP, metalloproteases, and prostaglandins, into the bloodstream and decrease the production of NO." (PMID 31817129, 2019). "Experimental periodontitis induces bone loss and an increase in the gingival MPO and plasmatic CRP." (PMID 30304126, 2018). "This may imply that the value of CRP for detecting systemic inflammation from periodontitis is weak in patients with cirrhosis." (PMID 29439734, 2018). "However, certain variables were included in few articles such as family history of periodontitis (11, 3.1%), genetics (11, 3.1%), C-reactive protein (9, 2.6%), creatinine (5, 1.4%), and albumin (2, 0.6%)." (PMID 30622957, 2018). "Thus, serum CRP and NE are elevated in patients with untreated periodontitis compared to healthy controls." (PMID 29484548, 2018). "Serum CRP level was reported to be elevated in subjects with periodontitis." (PMID 28243243, 2017). "Several studies have shown a positive relationship between CRP blood levels and periodontitis." (PMID 29085294, 2017). "A cohort prospective study showed periodontitis increases the level of CRP during pregnancy." (PMID 29017560, 2017). "In Aurer study on different groups including chronic periodontitis patients, healthy group, and patients with tooth loss showed that in addition to TNF-α, salivary levels of other inflammatory factors such as C3, CRP, and α-2M were lower in periodontitis group compared to other groups." (PMID 29238418, 2017). "Serum IL-6 and C-reactive protein levels are high in people with periodontitis." (PMID 27115749, 2016). "We discovered that systemic exposure to major periodontal pathogens, A. actinomycetemcomitans (but not P. gingivalis), and signs of oral infection, severe periodontitis, as well as elevated CRP and BMI are associated with the presence of MS." (PMID 26871443, 2016). "Several studies have also reported elevated CRP levels in periodontitis patients." (PMID 26871443, 2016). "Furthermore in a recent study of association between specific clinical parameters of periodontitis and systemic biomarkers, BOP was the only periodontal parameter significantly associated with systemic parameters of CRP, FIB, and WBC." (PMID 27034903, 2016). "The study also evaluated whether titers of IgG antibody to periodontopathic bacteria were correlated with their amount in saliva and CRP levels in patients with MS and periodontitis." (PMID 26871443, 2016). "A Swedish study showed median CRP of 2 mg/L in periodontitis patients." (PMID 26346216, 2015).
periodontitis (continued). "The lowest CRP levels were found in patients with gingival recessions, increasing in patients with gingivitis and patients with chronic periodontitis, with the highest levels found in aggressive periodontitis patients." (PMID 26346216, 2015). "Thus, the aim of this study was to compare and evaluate the systemic levels of CRP in the peripheral blood samples of patients with chronic and aggressive periodontitis, gingivitis, and gingival recessions and compare them with periodontal clinical parameters." (PMID 26346216, 2015). "Therefore, our findings of high eotaxin, MCP-1, and CRP systemically in periodontitis patients suggest a potential link to metabolic diseases." (PMID 26241961, 2015). "Another study evaluated the local effects of RvE1 on periodontitis in rabbits and showed that the anti-inflammatory effects of this bioactive product of omega-3 are due to a reduction in the systemic infla-mmatory markers, C-reactive protein and IL-1β." (PMID 24711890, 2014). "Therefore, further studies should focus on the relationship between periodontitis, elevated CRP & TNF-α levels and the effect of periodontal therapy on serum inflammatory markers concentration." (PMID 24198887, 2013). "In general population, also, evidence shows that moderate to severe periodontitis can contribute to inflammatory burden by increasing serum CRP levels and may increase the prevalence of atherosclerotic events." (PMID 23840952, 2013). "Another study evaluated hypertensive patients with periodontitis and showed that periodontal therapy might reduce levels of CRP and fibrinogen." (PMID 24010954, 2013). "Our study also shows an increase of the amount of saliva CRP in patients with periodontitis." (PMID 24551806, 2013). "In conclusion, periodontitis might increase serum CRP levels and other serum inflammatory markers, but efficient periodontal therapy could decrease CRP values." (PMID 23840952, 2013). "They showed that salivary CRP levels in the control group was lower than the other two groups and there was no significant diff-erences between the diabetic and non diabetic patients with periodontitis." (PMID 24551806, 2013). "This study also suggests the relationship between saliva CRP and periodontitis." (PMID 24551806, 2013). "The present study was performed to determine whether presence of periodontitis and periodontal therapy could influence the serum levels of CRP & TNF-α in cardiovascular disease patients." (PMID 24198887, 2013). "Elevated CRP & TNF-α level in periodontitis patients have been reported by several groups." (PMID 24198887, 2013). "Since periodontitis is a chronic disease of infectious origin, orosomucoid appears to be a better inflammatory marker than CRP in the morbidly obese, who display a chronic increase in CRP." (PMID 23526947, 2013). "The aftermath of inflammatory progression of periodontitis systemically leads to production of mediators in the vicinity such as C-reactive protein (CRP), interleukins-1beta (IL-1β), tumor necrosis factor-alpha (TNF-α) and interleukin 6 (IL-6) i.e Proinflammatory cytokines." (PMID 24198887, 2013). "Given that periodontitis is associated with only moderate elevations of CRP and erythrocyte sedimentation rate levels, the higher DAS28 scores observed in RA patients with periodontitis can only partly be explained by these higher levels due to periodontitis." (PMID 23075462, 2012). "Several reports have demonstrated elevated serum CRP levels in patients with periodontitis compared with healthy controls and some clinical studies have suggested that successful non-surgical periodontal treatment can reduce CRP levels in systemically healthy subjects." (PMID 22322513, 2012). "Patients who had both severe and moderate periodontitis had higher mean CRP levels." (PMID 23019501, 2011).
periodontitis (continued). "In fact, case-control and intervention studies have clearly demonstrated that high-sensitivity C-reactive protein (hs-CRP) and interleukin (IL)-6 protein levels are higher in cases of periodontitis and that successful treatment of periodontitis decreases the levels of both mediators." (PMID 21625524, 2011). "Particularly, Periodontitis increases the systemic levels of CRP, IL-6 and leucocytes, which may increase the inflammatory activity in atherosclerotic lesions and in consequence potentially increase the risk of cardiac and cerebrovascular events." (PMID 28348657, 2011). "Therefore, CRP levels were significantly elevated among individuals with severe periodontitis (8,25 mol/L), and among individuals with moderate periodontitis (4,93 mol/L) than in the controls (1.09 mol/L)." (PMID 23019501, 2011). "Increased blood levels of HbA 1c, CRP, and cytokines supported the idea that periodontitis may affect or worsen systemic diseases." (PMID 22203908, 2011). "In this study, a first aim was to evaluate levels of CRP in patients with periodontitis, as well as to examine whether CRP plasma level is in a relation to severity of periodontitis and presence of pathogens in a Serbian population in Nis." (PMID 23019501, 2011). "The present study was undertaken to examine whether serum levels of CRP and IL-6 are increased in periodontitis, and to determine the relationship of their elevated levels to the severity of periodontal disease." (PMID 20407653, 2009). "Periodontitis results in higher systemic levels of CRP and IL-6." (PMID 20407653, 2009). "The elevated levels of CRP and IL-6 in periodontitis patients may occur when bacteria and bacterial products, such as lipopolysaccharide (LPS), as well as locally produced pro-inflammatory cytokines enter the circulation." (PMID 20407653, 2009). "More recent evidence, however, has indicated that patients with severe periodontitis have increased serum levels of CRP, hyperfibrinogenemia, moderate leukocytosis, as well as increased serum levels of IL-1 and IL-6 when compared with unaffected control populations." (PMID 20407653, 2009). "C-reactive protein (CRP), an acute-phase reactant synthesized by the liver in response to inflammatory cytokines, is frequently elevated in systemic inflammatory conditions, including both chronic and aggressive forms of periodontitis as well as cardiovascular disease." (PMID 41586318, 2025). "Additionally, several studies indicate that treating periodontitis may help reduce other CVD risk factors, such as lowering C-reactive protein (CRP) levels and improving endothelial function, both clinically and through surrogate measures." (PMID 40001895, 2025). "While the coexistence of periodontitis and elevated CRP levels may increase the risk of mortality; no previous study has confirmed their synergistic effect." (PMID 39453923, 2024). "Another study examined an additional etiological mechanism, specifically investigating whether circulating serum C-reactive protein (CRP) levels and a weighted genetic CRP score, which represents inflammatory markers, may alter the relationship between periodontitis and NAFLD." (PMID 39200318, 2024). "After adjustment for covariates, there was strong evidence for an association between PISA and vWF, but the associations between periodontitis one the one hand with CRP and HDL-c levels seen in the groupwise analysis did not persist after adjusting for confounders." (PMID 39212739, 2024). "Considering the systemic risks associated with increased serum CRP levels and the observed decrease in CRP concentrations following nonsurgical therapy in periodontitis patients with concurrent CVD, immediate infection control in these individuals is imperative." (PMID 38667035, 2024). "In conclusion, individuals with periodontitis and high CRP levels might show a high mortality rate." (PMID 39453923, 2024). "Additionally, its interaction with CRP underscores its significance in periodontitis pathogenesis." (PMID 39453923, 2024).
periodontitis (continued). "Crude survey-weighted Cox models revealed that the periodontitis status (present or absent) and CRP levels (≤ 0.5 mg/dL or > 0.5 mg/dL) were associated with mortality, demonstrating HRs of 3.0 (95% CI, 2.54–3.55) for periodontitis status and 1.37 (95% CI, 1.08–1.74) for the CRP levels." (PMID 39453923, 2024). "In addition, the associations of periodontitis status and CRP levels with mortality were also found to be significant in the multivariate model including all confounders, with HRs of 1.29 (95% CI, 1.03–1.61) and 1.44 (95% CI, 1.16–1.78) for periodontitis status and CRP level, respectively." (PMID 39453923, 2024). "CRP levels were comparable across combinations of periodontal health conditions and MetS components, with the only exception of the finding of significantly higher CRP levels in individuals with unstable periodontitis and concomitant low HDL-c compared with periodontally healthy individuals." (PMID 37038173, 2023). "While several limitations exist within the study, including a small sample size and a lack of negative controls, it is feasible to suggest that both C-reactive protein and periodontitis could be associated with adverse pregnancy outcomes." (PMID 37511934, 2023). "Also, the treatment of periodontitis induced a significant decrease in CRP levels." (PMID 37214190, 2023). "Finally, a recent meta-analysis showed that salivary CRP is a reliable alternative for plasma CRP for the diagnosis and management of medical conditions and oral disorders, including oral lichen planus and periodontitis cases (other medical conditions with be reported in the next section)." (PMID 37873776, 2023). "In addition, IL-6 levels affected CRP levels in moderate–severe periodontitis patients with CAD." (PMID 37239434, 2023). "Therefore, it is hypothesized that CRP may act as a potential mediator in the relationship between periodontitis and these systemic diseases." (PMID 38077410, 2023). "Therefore, the null hypothesis for this study stated that the periodontal therapy in chronic periodontitis doesn’t influence the CRP levels." (PMID 37568846, 2023). "Overall, inflammation mediated by CRP/IL-6 may connect RC and periodontitis occurrence." (PMID 36824233, 2023). "In addition, the high expression of C-reactive protein (CRP) could be detected in the serum of patients with periodontitis." (PMID 36131931, 2022). "The influence of local inflammation of periodontitis occurring in a large proportion of the oral cavity may significantly contribute to systemic inflammation mediated by C-reactive protein and main inflammatory cytokines such as tumor necrosis factor alpha, interleukin 1b and interleukin 667,68." (PMID 35922537, 2022). "Moreover, it significantly prevented periodontal tissue loss during periodontitis in vivo without the influence of mouse body weight, serum CRP, and organ damage, indicating its potential therapeutic effects in periodontitis." (PMID 35720191, 2022). "Alternatively, during periodontitis, inflammatory mediators and/or microbial components diffuse systemically from the oral cavity to the liver, enhancing cytokine production (e.g., IL-6) and acute phase protein responses (e.g., CRP), which then impact the fetal–placental unit." (PMID 35207626, 2022). "In the other part, periodontitis, through bacteria or their virulence factor translocation, act like a constant challenge to immune inflammatory cells, increasing the release of pro-inflammatory mediators (CRP, TNF-α, IL-6, and IL-1β) and periodontal-derived EVs into circulation." (PMID 34769262, 2021). "Hence, our study may be underpowered to detect the increases in CRP reported in other cohorts of patients with periodontitis." (PMID 33368493, 2021).
periodontitis (continued). "Indeed, when contrasted with healthy subjects, patients with periodontitis present higher values of circulating white blood cells as well as other systemic inflammatory parameters such as C-reactive protein (CRP), a protein produced by the liver as a response to external stress." (PMID 34776994, 2021). "Interestingly, serum CRP levels modified the interaction between periodontitis and NAFLD." (PMID 33918456, 2021). "Inflammatory mediators arising from periodontitis may stimulate hepatocytes to produce CRP." (PMID 32994872, 2020). "Furthermore, C-reactive protein (CRP), a protein that its level increases in acute inflammation, was also reported in literature to be associated with periodontitis and cardiovascular diseases that can put individuals at higher risk of developing the disease or to worsen the condition." (PMID 32000769, 2020). "Although, the fact that periodontitis may be associated with changes in the levels of inflammatory markers makes the systemic impact of periodontal alterations relevant, few studies have assessed the relationship between periodontitis and altered levels of CRP." (PMID 32994872, 2020). "Moreover, periodontitis increases serum hs-CRP levels, which may mediate the increase in serum MAA levels, as shown by many groups." (PMID 31805680, 2019). "Moreover, the association between both saliva and serum vitamin C levels were assessed, and whether salivary or serum vitamin C levels were mediated by serum CRP in patients with periodontitis and with CAD." (PMID 31817129, 2019). "A possible explanation of the high proportion of CRP levels in patients with periodontitis compared to healthy controls could be due to the strong impact exerted by periodontopathogenic bacteria on systemic inflammation mediated by a CRP pathway, mainly measured by CRP and interleukin 6 (IL-6)." (PMID 31817862, 2019). "Intriguingly, CRP seems to mark a similar systemic low-grade inflammation in the two groups, suggesting a primary involvement of the mouth–gut axis, with a key role of the periodontitis and the oral inflammation as the main determinant of the observed hormone variations." (PMID 30451975, 2019). "Numerous reports have shown that periodontitis could raise the serum pro-inflammatory state, characterized by increased levels of C Reactive Protein (CRP) and pro-inflammatory cytokines (e.g. TNF-α), and decreased levels of anti-inflammatory markers (e.g. IL-10)." (PMID 29422938, 2018). "Within the limitations of the present study, the following conclusion may be drawn: Despite comprehensive periodontal therapy and significant clinical improvement NE and CRP levels in patients with aggressive periodontitis are elevated compared to patients with untreated chronic periodontitis." (PMID 29484548, 2018). "Similarly, although 2 studies from the same group suggest that reduced levels of the acute phase protein C-reactive protein (CRP) in saliva are associated with periodontitis, data from other studies are not consistent with this finding." (PMID 24944840, 2014). "Indeed, the data of the present study do not show any association between CRP, IL-6, leptin or adiponectin with periodontitis in morbidly obese patients." (PMID 23526947, 2013). "Elevated systemic markers, such as C-reactive protein (CRP) and interleukin-6 (IL-6), are frequently observed in both periodontitis and these comorbidities, indicating a convergence of pathological pathways." (PMID 41590813, 2026). "The local and systemic immunological effects of chronic apical periodontitis and the impact of combined RCT and surgical treatment on serum CRP levels in populations with good general health have been previously reported." (PMID 39797322, 2025). "Within the limitations of this retrospective study, non-surgical periodontal therapy was associated with significant reductions in systemic inflammatory biomarkers (CRP, IL-1β, IL-6, TNF-α) across all stages and grades of periodontitis." (PMID 41440349, 2025).